MIP (major intrinsic protein of lens fiber)
Diseases named in the same sentence as MIP in open-access papers (continued):
Sharing a sentence is not in itself a finding about the gene and the disease.
autosomal dominant congenital cataracts (9 papers, 2010 to 2025). "In summary, we reported autosomal dominant congenital cataracts caused by a novel p.K228fs frameshift mutation in the MIP gene in a four-generation Chinese family." (PMID 29695758, 2018). "In summary, we have described a novel nonsense mutation in MIP causing autosomal dominant congenital cataracts in a Chinese family." (PMID 25803033, 2015). "In summary, our study presented genetic and functional evidence linking the new MIP mutation of G215D to autosomal dominant congenital cataracts, which adds to the list of MIP mutations linked to congenital progressive punctate cataracts." (PMID 25033405, 2014). "In this study, we have described the first nonsense mutation in MIP causing autosomal dominant congenital cataracts in a large Chinese family." (PMID 24405844, 2014). "In summary, the current study presented genetic and functional evidence linking a new mutation of MIP (G215D) to autosomal dominant congenital cataracts." (PMID 25033405, 2014). "In 2000, the major intrinsic protein (MIP, MP26, AQP0) was reported to be associated with autosomal dominant congenital cataract (ADCC)." (PMID 21139677, 2010). "In the present study, we identified the molecular and functional defects in three generations of a Chinese family with autosomal dominant congenital cataracts (ADCC), and detected a novel c.634G > C transition in exon 4 of the MIP gene by target region capture sequencing." (PMID 28059152, 2017).
anemia (5 papers, 2011 to 2023). A reduction in the number of red blood cells, the amount of hemoglobin, and/or the volume of packed red blood cells. "The extent of MiP-associated anemia seems to be higher in primigravidae/secundigravidae and ANC patients." (PMID 37927870, 2023). "MiP compounds or provokes maternal anaemia, which when severe, increases the risk of maternal death: it has been estimated that malaria-related anaemia causes around 10 000 maternal deaths annually." (PMID 21799859, 2011). "However, it is important to avoid expanding MiP interventions to the detriment of other core health issues, such as anaemia and miscarriage, some of which can be linked to MiP but whose aetiologies are more complex." (PMID 23876079, 2013). "The mechanisms by which P. vivax infections lead to MiP outcomes are still unclear; yet, systemic events such as maternal anemia and generalized inflammation have been discussed as relevant to P. vivax MiP pathology." (PMID 33914739, 2021). "However, specific markers of MiP result in poor outcomes, such as low birth weight, and intrauterine growth restriction for babies and maternal anemia in women infected with Plasmodium falciparum are limited." (PMID 37628675, 2023).
diabetes (5 papers, 2013 to 2022). "The incidence of diabetes occurred at an earlier time point in female MIP-Luc-VU-NOD mice than male mice." (PMID 23483929, 2013). "Using our model of STZ-diabetic MIP-luc mice, treatment of Pio plus alogliptin starting from the time of diabetes diagnosis when the bioluminescent signal was 0.5–8% of baseline prior to STZ-treatment, prevented the further decay in bioluminescent signal observed in non-Pio-treated controls." (PMID 23762423, 2013).
breast carcinoma (4 papers, 2019 to 2022). "In contrast to nontreated con cells, for senescent human breast cancer MDA-MB-231 cells, the factors detected by arrays and secreted at a significant level are FGF-6, GM-CSF, IGFBP-1, MCP-1, IL-6, IL-1α, GRO a/b/g, GRO α, IL-8, MIP, MIP-1α, uPAR, ICAM-1, and MMP-1." (PMID 30871042, 2019).
COVID-19 (4 papers, 2021 to 2024). A disease caused by infection with severe acute respiratory syndrome coronavirus 2. "Orumaa and co-authors revealed that severity of COVID-19 is linked to cytokine storm, which occurs when levels of inflammatory mediators such as IL-7, IL-10, and MIP are up-regulated." (PMID 37053191, 2023). "MIP serum levels were found to be elevated in patients with COVID-19, requiring ICU admission." (PMID 34540715, 2021). "Meanwhile, five proteins exert protective effects against hospitalization and progression to critical COVID-19 (OR: 0.85~0.95), including CXCL11, CDCP1, CCL4/MIP, IFNG, and LIFR." (PMID 38455043, 2024). "Another hypothesis for the cardiac involvement in COVID-19 implicates the systemic release of pro-inflammatory cytokines (e.g., IL-1, IL-6, TNF-α, IFN-γ, and MIP) and the subsequent “cytokine storm” as the main culprit with subsequent increased vascular wall permeability and myocardial edema." (PMID 36371548, 2023).
tuberculosis (4 papers, 2013 to 2023). A chronic, recurrent infection caused by the bacterium Mycobacterium tuberculosis. "MIP has been used as a promising immuno-modulator against M. tuberculosis in the guinea pig model of TB." (PMID 31060300, 2019). "It was suggested that MIP had a clear effect on M. tb, but another phase 3 clinical trial found that MIP was not effective as an adjunct to antituberculosis therapy in patients with TB pericarditis." (PMID 38022657, 2023). "After M. tuberculosis infection, macrophages are activated locally and chemokines increase, leading to a gradual increase in serum MIP level from non-infection and LTBI to active TB." (PMID 23356448, 2013).
chronic periodontitis (2 papers, 2020 to 2025). A chronic inflammatory process that affects the tissues that surround and support the teeth. "This study shows for the first time that C/MIP cases have higher Immunoglobulin G levels than controls in saliva and gingival crevicular fluid, confirming its association with C/MIP pathogenesis and suggesting that it could be a potential biomarker in grade C molar incisor pattern periodontitis." (PMID 40159446, 2025). "Saliva IgG is known to be elevated in patients with chronic and aggressive periodontitis, and our saliva findings indicate that IgG was elevated in young C/MIP patients." (PMID 40159446, 2025).
fetal growth restriction (2 papers, 2020 to 2023). A fetus that does not grow beyond the 10th percentile of conventionally accepted weight for gestational age. "MiP is a key player in fetal growth restriction and subsequent birth outcome." (PMID 32854715, 2020).
leprosy (2 papers, 2018 to 2022). Leprosy is a chronic infectious disease affecting primarily the skin and peripheral nervous system. "MIP has been tested for its putative therapeutic efficacy in tuberculous pericarditis and for its protective efficacy against leprosy." (PMID 29535713, 2018). "In this study, the protective efficacy of MIP in vaccinated household contacts after 3 years was the highest ever reported against leprosy (68%) for a vaccine other than BCG." (PMID 29535713, 2018). "MIP has been studied as an adjunct therapy for leprosy and has been shown to have both immunoprophylactic and immunotherapeutic effects and the duration of multi-drug therapy in leprosy patients by improving the immune responses to M. leprae." (PMID 35812462, 2022). "Besides BCG, only MIP and killed M. vaccae have been clinically evaluated for both leprosy and TB, although in different trial designs and target populations." (PMID 29535713, 2018).
Stillbirth (2 papers, 2018 to 2019). Death of the fetus in utero after at least 22 weeks of gestation. "Standardized definitions and accurate measures for abortion, preterm delivery, stillbirth and placental malaria in the context of murine MiP." (PMID 31275284, 2019). "In fact, the very low stillbirth incidence for the heterogenic Tlr4−/−/Tlr4+/− maternal-fetal combination implies that TLR4 acts in the fetal compartment to confer robust protection against increased stillbirth incidence in MiP." (PMID 29440369, 2018).
acute respiratory distress syndrome (1 paper, 2015). Progressive and life-threatening pulmonary distress in the absence of an underlying pulmonary condition, usually following major trauma or surgery. "Previous studies have demonstrated that highly elevated IL-6, IL-1, TNF-α, IFN-γ, MIP, CXCL10 are major causes of ARDS (acute respiratory distress syndrome) and mortality, and TGF-β1 could restrict inflammatory response." (PMID 25909459, 2015).
Age-related nuclear cataract (1 paper, 2024). A type of age-related cataract that primarily affects the nucleus of the lens. "Variants in many genes underlying inherited forms of cataract (e.g., BFSP1, LIM2, MIP, and CHMP4B) have been shown to exhibit tentative association with age-related nuclear cataract." (PMID 38927721, 2024).
Anxiety (1 paper, 2020). Intense feelings of nervousness, tension, or panic often arise in response to interpersonal stresses. "In addition, MIP, a biomarker of the innate immune system, was also increased in patients with BMS and weakly positively correlated with anxiety and depression scores, suggesting that the immune system is implicated in the pathogenesis of BMS." (PMID 32231113, 2020).
atherosclerosis (1 paper, 2026). A disease characterized by the build-up of fatty material and calcium deposition in the arterial wall resulting in partial or complete occlusion of the arterial lumen. "miP-PSTPIP2 expression was upregulated in IL-1β-treated human endothelial cells, in pre-atherosclerotic murine carotid arteries and detected in carotid arteries from patients with atherosclerosis." (PMID 42156223, 2026).
chlamydial infections (1 paper, 2013). "In addition further immunoreactive proteins could be identified such as the homologues of CPAF (CAB712), MIP (CAB080), TARP (CAB167), and PMPD (CAB776); all of them were also discussed as virulence associated factors in other chlamydial infections." (PMID 24260366, 2013).
colorectal cancer (1 paper, 2008). A primary or metastatic malignant neoplasm that affects the colon or rectum. "We assessed the methylation status of four colorectal cancer cell lines (MIP101, RKO, HT29, and HCT 116) and one normal colon cell line (CCD 112CoN) and observed hypermethylation in the promoter region of MIP 101 and RKO cells flanked by both MSP1 and MSP2." (PMID 18458674, 2008).
falciparum malaria (1 paper, 2019). "The IL-10 production during MiP-associated chronic inflammation is a hallmark of falciparum malaria during pregnancy that had been associated with poor pregnancy outcomes and considered as a possible MiP biomarker." (PMID 31805150, 2019).
glioma (1 paper, 2017). A benign or malignant brain and spinal cord tumor that arises from glial cells (astrocytes, oligodendrocytes, ependymal cells). "Glioma cells produce various inflammatory mediators, such as IL-1β, IL-6, IL-8, IL-10, MCP-1, and MIP." (PMID 28881826, 2017).
Hyperglycemia (1 paper, 2013). An increased concentration of glucose in the blood. "Male MIP-Luc-VU-NOD that became diabetic also demonstrated a decline in bioluminescence intensity prior to the onset of hyperglycemia." (PMID 23483929, 2013). "These mice, known as MIP-Luc-VU-NOD, developed hyperglycemia progressively with increasing age, with a higher incidence and earlier age of onset in female mice compared with male mice, as previously demonstrated in other NOD colonies." (PMID 23483929, 2013).
infertile (1 paper, 2021). "Four (GLC, TG, CHOL, and miP) out of the nine analytes studied were found to be significantly altered in the infertile patients." (PMID 34698062, 2021).
insulinoma (1 paper, 2019). "Priming with CM prepared from the culture supernatants of the syngeneic (MIN-6) or xenogeneic (INS-1) insulinoma cell lines directed the MIP-Luc/GFP derived BMNCs to express GFP within 6 days." (PMID 30926860, 2019).
left ventricular non-compaction cardiomyopathy (1 paper, 2021). "Mutations in the MIPEP gene, (encoding the octapeptidyl peptidase MIP, also known as Oct1 in yeast) have been found associated with left ventricular non-compaction cardiomyopathy (LVNC), hypotonia and developmental delay." (PMID 34356047, 2021).
lung carcinoma (1 paper, 2022). "In addition, the generality of the model will be studied to make MIP-MY model suitable for the detection of common lung diseases, including lung cancer and pneumonia." (PMID 35401735, 2022).
meningioma (1 paper, 2021). A generally slow growing tumor attached to the dura mater. "In terms of tumour recurrence, lower TGF-ß expression and higher expression of OPN, HGF/SF, MIP and MMP-9 were found to correlate significantly with the recurrence of meningiomas." (PMID 34503077, 2021).
myopia (1 paper, 2023). "Although the downstream targets of key myopia genes predicted by WGCNA and DEG analysis were not among the predicted targets of DZP, the molecular docking results showed that MIP and LGSN could firmly bind to the active constituents of DZP." (PMID 37747014, 2023).
Nystagmus (1 paper, 2018). Rhythmic, involuntary oscillations of one or both eyes related to abnormality in fixation, conjugate gaze, or vestibular mechanisms. "In addition, all patients with MIP variants identified in this study had nystagmus." (PMID 29914532, 2018).
pancreatitis (1 paper, 2023). Inflammation of the pancreas. "In patients with pancreatitis and a pancreatic duct variation that drains mainly through the MiP (types 2, 4) the obstruction of pancreatic juice outflow may be aggravated, which deserves further observation and research." (PMID 36766625, 2023). "However, the MiP easily accumulates and stagnates due to the small physiological opening, which may lead to pancreatitis." (PMID 36766625, 2023).
parasitemia (1 paper, 2018). "Together, these results suggest that the maternal IFNAR1 action in MiP pathogenesis favors increased peripheral parasitemia and possibly contributes to fetal weight loss." (PMID 29440369, 2018).
placental insufficiency (1 paper, 2021). Failure of the placenta to deliver an adequate supply of nutrients and oxygen to the fetus. "Dysregulation of angiogenic and inflammatory factors are often associated with placental insufficiency and impaired fetal development in P. falciparum MiP." (PMID 33914739, 2021).
Punctate cataract (1 paper, 2014). A type of cataract with punctate opacities of the lens. "In the present study, we identified that the p.G215D mutation of MIP was linked to congenital progressive punctate cataracts in a three-generation Chinese family." (PMID 25033405, 2014). "In the present study, a novel mutation of the MIP gene was identified in exon 4 at nucleotide 644, which caused a substitution of glycine to aspartic acid at codon 215 (p.G215D) in a Chinese family with congenital progressive punctate cataracts." (PMID 25033405, 2014).
rickets (1 paper, 2012). Bone softening and weakening usually caused by deficiency or impaired metabolism of vitamin D. Deficiency of calcium, magnesium, or phosphorus may also cause rickets. "The lack of MCa and MIP causes malformation of the skeletal system and rickets, while a high level of these minerals in the milk of healthy cows is an appropriate condition in milk production." (PMID 25653747, 2012).
Sepsis (1 paper, 2024). Sepsis is defined as life-threatening organ dysfunction caused by a dysregulated host response to infection. "According to the specific interactions between MiP and prematurity, it is essential to understand the dysfunctions of regulatory immunity related to the risk of sepsis in a group of newborns affected by MiP and prematurity." (PMID 39072327, 2024).
type 1 diabetes (1 paper, 2013). "Building upon our previous experience using bioluminescence imaging to measure beta cell mass, we bred MIP-Luc-VU mice, which express a luciferase optical reporter gene in the beta cell, with the NOD mouse, a widely used model of type 1 diabetes." (PMID 23483929, 2013).
infection (22 papers, 2011 to 2026). The state of being infected such as from the introduction of a foreign agent such as serum, vaccine, antigenic substance or organism. "In this analysis, infants born to mothers who were exposed to ≥1 infection of MiP or placental malaria were at higher risk of impaired growth during the first year of life, which is consistent with results from two previous studies showing that MiP affects growth beyond the in utero period." (PMID 26879849, 2016). "During MiP, trophoblasts produce chemokines upon parasite recognition, recruiting monocyte-producing cytokines and ROS to clear local infection." (PMID 35898514, 2022). "Through Ct-protein array screening of serum from children resistant or susceptible to frequent and/or prolonged Ct infection, we identified three susceptibility associated surface antigens CT017 (Ctad1), CT541 (MIP) and CT579." (PMID 28851925, 2017). "Specifically, pro-inflammatory cytokine (e.g. IL-1α, MIP, and TNFα) levels rise, enhancing neutrophils migration to the infection site." (PMID 29117213, 2017). "The relative stability of functional opsonizing antibodies even with low force of infection, compared with IgG directed to recombinant antigens, makes their levels a potential measure of longer lasting immunity to MiP." (PMID 26006260, 2015). "We transferred a 3-gene combination of Pdx1, Neurod, and Mafa into the MIP-Luc-VU mice with different infectious titers to detect the bioluminescence signal 3 days after infection, according to a previous study." (PMID 25397325, 2014). "Therefore, monoclonal antibodies, targeting either the domains of VAR2CSA or the circumsporozoite protein to prevent establishment of infection can be further developed as therapeutics for MiP." (PMID 33790894, 2021). "It is currently unknown whether this represents a compensatory mechanism to circumvent decreased placental P‐gp and BCRP expression induced by MiP, or if this is an inherent response to MiP infection." (PMID 32779889, 2020). "Additionally, we observed a decrease of peripheral Ang-1 in women with a current infection and a significantly higher ratio of Tie-2:Ang-1 in both the total women who had MiP or only the women who had a current infection, relative to the uninfected women." (PMID 26090803, 2015). "In addition, studies have provided evidence of a link between infection-induced inflammation during pregnancy and placental autophagy, which might be critical for dysregulating placental homeostasis, contributing to poor outcomes during pregnancy-related diseases, such as MiP." (PMID 35898514, 2022). "We evidenced that early-MiP–infection occurring only in the first trimester and not after–was significantly associated with a higher risk of infection in infant during the first 3 months of life." (PMID 31536589, 2019). "While it has been shown that nutrient transport is impaired in MiP, there is still little evidence on the mechanisms that alter placental physiology during infection." (PMID 29440369, 2018).